GNAS (GNAS complex locus)
Diseases named in the same sentence as GNAS in open-access papers (continued):
Sharing a sentence is not in itself a finding about the gene and the disease.
fibrous dysplasia (continued). "Fibrous dysplasia (FD) is a bone marrow stromal cell (BMSC) disease caused by activating mutations of guanine nucleotide-binding protein alpha-stimulating activity polypeptide (GNAS) and is characterized by increased proliferative activity and disrupted osteogenesis of BMSCs." (PMID 34294046, 2021). "Additionally, GNAS mutations and c-Fos are also involved in the pathogenesis of fibrous dysplasia." (PMID 30111377, 2018). "Fibrous dysplasia/McCune-Albright syndrome (FD/MAS) is a rare and complex condition caused by somatic variants in the GNAS gene that lead to a wide clinical spectrum." (PMID 40316789, 2025). "Fibrous dysplasia/McCune–Albright syndrome (FD/MAS) is a rare disorder of striking complexity, resulting from recurrent somatic gain-of-function mutations in the GNAS locus, which is located on chromosome 20q13.3." (PMID 40297189, 2025). "Among BFOLs, two diseases have been well-characterized, fibrous dysplasia (FD) and hyperparathyroidism-jaw tumor syndrome (HPT-JT) (OMIM:145001), caused by specific gene mutations, GNAS and HRPT2/CDC73, respectively." (PMID 35454175, 2022). "Fibrous dysplasia (FD) of the bone (OMIM #174800, ORPHA: 249) is a rare genetic bone disorder caused by postzygotic activating variants (primarily at the R201 and more rarely at Q227 codons) in GNAS, which encodes the α subunit of stimulatory G protein (Gαs)." (PMID 40781626, 2025). "Fibrous dysplasia/McCune-Albright syndrome (FD/MAS) is a rare disorder (estimated prevalence between 1/100,000 and 1/1,000,000), caused by a post-zygotic gain of function somatic variant in the GNAS gene leading to a broad clinical spectrum." (PMID 40316789, 2025). "Fibrous dysplasia (FD) is a nonhereditary bone disease caused by GNAS gene mutation in bone marrow stromal cells (BMSCs); in FD, normal bone tissue is replaced by overproliferated fibrous tissue and immature trabecular bone." (PMID 34294046, 2021). "In a recent review by our group that updated the GNAS genetic mutation rate of in fibrous dysplasia was up to 86% (264/307), while no mutation was found in patients diagnosed with ossifying fibroma." (PMID 24678936, 2014). "For example, patients with isolated monostotic and polyostotic fibrous dysplasia have been shown to display activating mutations in GNAS without the full spectrum of McCune Albright syndrome." (PMID 23663565, 2013). "However, several fibrous dysplasias were not showing a GNAS mutation in their study regardless of the molecular methods used, including deoxyribonucleic acid sequencing, allele-specific polymerase chain reaction, and high resolution melting analysis." (PMID 38539216, 2024). "Concerning molecular analysis for OFD, somatic mutations of the guanine nucleotide-binding protein/a-subunit (GNAS) gene might lead to monostotic fibrous dysplasia, polyostotic fibrous dysplasia, McCune–Albright syndrome, and soft tissue myxoma coexisting with fibrous dysplasia." (PMID 38539216, 2024). "The fibrous dysplasia patients without measurable GNAS mutation might be interpreted by the tumoral mosaicism of fibrous dysplasia, with high proportions of non-mutated cells compared with mutated cells." (PMID 38539216, 2024). "Fibrous dysplasia (FD) is a rare, non-inherited bone disease occurring following a somatic gain-of-function R201 missense mutation of the guanine-nucleotide binding protein alpha subunit stimulating activity polypeptide 1 (GNAS) gene." (PMID 36768871, 2023). "Additionally, mutational testing for GNAS can also be useful since GNAS mutations are specific for fibrous dysplasia and are not present in other fibro-osseous lesions, including low-grade osteosarcomas." (PMID 35875137, 2022). "GNAS mutations that are specific for fibrous dysplasia are absent in low-grade OS." (PMID 29244987, 2017). "Fibrous dysplasia could be excluded from the differential diagnosis since a negative GNAS1-mutational status (GNAS 1 wild type) was identified." (PMID 27585859, 2016).
fibrous dysplasia (continued). "Due to the biological features of fibrous dysplasia, a high recurrence rate associated with curettage is possible, regardless of with or without bone grafting, because not all of the cells containing the mutation of the GNAS gene can be removed." (PMID 25407316, 2014). "Fibrous dysplasia (FD) is a non-malignant condition caused by post-zygotic, activating mutations of the GNAS gene that results in inhibition of the differentiation and proliferation of bone-forming stromal cells and leads to the replacement of normal bone and marrow by fibrous tissue and woven bone." (PMID 22640797, 2012).
McCune-Albright syndrome (65 papers, 2007 to 2026). McCune-Albright syndrome (MAS) is classically defined by the clinical triad of fibrous dysplasia of bone (FD), cafe-au-lait skin spots, and precocious puberty (PP). "McCune-Albright syndrome is a rare genetic disorder, arises from a somatic activating mutation of a GNAS gene encoding a guanine nucleotide-binding protein G(s) subunit alpha." (PMID 40861765, 2025). "Fibrous Dysplasia / McCune Albright Syndrome (FD/MAS) is a rare disease that arises following somatic activation mutations of the GNAS gene, which codes for the α-subunit of the Gs stimulatory protein." (PMID 38326833, 2024). "This is a condition that, when associated with cutaneous hyperpigmentation and endocrinological disorders, forms the classic triad of McCune-Albright syndrome, a rare multisystemic pathology formed by postzygotic somatic mutations of the GNAS gene." (PMID 38073973, 2023). "Fibrous dysplasia (FD) is due to activating mutations in GNAS observed in McCune-Albright syndrome (MAS), which is characterized by FD of bone, café-au-lait spots, and precocious puberty, resulting in increased FGF23-synthesis in bone." (PMID 34910242, 2022). "McCune Albright Syndrome (MAS) is caused by a mutation in the GNAS gene that results in multiple endocrinopathies such as Cushing syndrome, acromegaly, hyperthyroidism, and precocious puberty." (PMID 33936872, 2021). "Many studies have found that mutations in GNAS are associated with human diseases; GNAS-activating mutations lead to McCune-Albright syndrome, while GNAS-inactivating mutations cause Albright’s hereditary osteodystrophy." (PMID 34907172, 2021). "GNAS-activating somatic, post-zygotic, mutations are also associated with McCune-Albright syndrome (MCAS) characterized by fibrous dysplasia, precocious puberty, and café-au-lait spots." (PMID 31852070, 2019). "The aim of the present study is to examine the mutation status of GNAS in a patient with McCune Albright Syndrome and IPMN who underwent pancreatic resection." (PMID 31852070, 2019). "Although GNAS mutations have been well-described in the McCune Albright syndrome, sporadic mutations of this gene have been reported in various neoplasms, including corticosteroid-producing adrenal tumors that can lead to Cushing’s syndrome." (PMID 30670014, 2019). "For example, from the observation that activating mutations in GNAS (associated with McCune-Albright syndrome, OMIM 174800) are detected only in the mosaic state, one can infer that constitutional activating mutations in this gene are incompatible with life." (PMID 31349857, 2019). "Genetic examination of the adrenal tumor revealed the somatic GNAS mutation p.R201H, which is known to be responsible for McCune-Albright syndrome, although sporadic GNAS mutations have also been reported." (PMID 30670014, 2019). "GNAS mutation was considered a marker of a benign or well-differentiated disease in the previous reports, including McCune-Albright syndrome, thyroid toxic nodules, pituitary adenoma, and ovarian granulosa cell tumor." (PMID 28423545, 2017). "Their etiology is incompletely understood, but they are frequently associated with mutations (e.g., GNAS) and may occur in syndromic conditions such as Mazabraud and McCune-Albright syndromes." (PMID 41827960, 2026). "Others of unilateral or bilateral ovarian cysts can also be observed in patients with McCune-Albright syndrome due to a somatic mutation in the GNAS gene (guanine nucleotide-binding protein, alpha stimulating), leading to ovarian autonomy and hyperestrogenism, with low FSH levels." (PMID 40626238, 2025). "The GNAS mutations were first identified in patients with McCune-Albright syndrome in 1991." (PMID 39135681, 2024). "Furthermore, mutations in the GNAS gene have been established as causative for McCune-Albright syndrome in humans, a condition known to involve endocrinologic anomalies such as Cushing syndrome." (PMID 39118059, 2024).
McCune-Albright syndrome (continued). "Besides variants in genes of the PI3K/AKT or RAS/MAPK pathways, somatic mosaicism in GNAQ or GNAS is associated with monogenic disorders such as Sturge-Weber syndrome (GNAQ variants) or McCune-Albright syndrome (GNAS variants)." (PMID 38835734, 2023). "Question 3: Which term best describes the GNAS gene mutation of McCune-Albright syndrome?" (PMID 36159720, 2022). "Somatic mosaicism of GNAS has been implicated in the pathogenesis of McCune-Albright syndrome-related adrenal Cushing syndrome manifesting as bilateral macronodular adrenocortical disease (e.g., PBMAH), as well as a bimorphic cortical nodular disease and rare adenomas." (PMID 29594118, 2018). "McCune-Albright syndrome (MAS) is a rare disorder due to somatic gain-of-function mutations of the GNAS gene, located on chromosome 20q13.3." (PMID 40584159, 2025). "McCune-Albright Syndrome (MAS) is a rare genetic disorder caused by somatic, postzygotic activating mutations in GNAS, a component of the protein kinase A (PKA) signaling pathway." (PMID 39896942, 2025). "Fibrous dysplasia/McCune-Albright Syndrome (FD/MAS) is a rare disease resulting from somatic gain-of-function GNAS mutations, which contributes to constitutive activation of G-protein coupled receptors." (PMID 35262711, 2022). "The role of abnormal cAMP-PKA signaling in adrenocortical tumorigenesis was first described in 1991 when early embryonic postzygotic somatic activating defects of the GNAS gene were implicated in the pathogenesis McCune-Albright syndrome (MAS)." (PMID 33776926, 2021). "The same in vitro and in vivo cystic phenotype was observed when PDLOs were established from iPSCs of a patient suffering from McCune-Albright syndrome (MAS), which is caused by postzygotic mosaic GNAS mutations." (PMID 34926472, 2021). "McCune-Albright Syndrome (MAS) is a proto-typical disease caused by activating mutations in the GNAS locus, encoding the Gsα protein." (PMID 32038487, 2019). "This is distinct from patients with activating GNAS mutations as seen with McCune-Albright Syndrome (MAS), who typically present with the classic triad of polyostotic fibrous dysplasia of the bone, café-au-lait skin hyperpigmentation, and precocious puberty." (PMID 27579188, 2016). "Additional extraskeletal manifestations of the GNAS mutation may be present in the McCune-Albright Syndrome (MAS), including endocrinopathies and skin hyperpigmentation." (PMID 36528764, 2022). "The involvement of this pathway was first identified in CS in McCune-Albright syndrome (MAS), which is caused by somatic-activating variants in the gene that encodes the α-subunit of the stimulatory G protein (Gsα), GNAS." (PMID 35625779, 2022). "GNAS: In children, the most common cause of Cushing’s syndrome of adrenal origin is the McCune Albright syndrome (MAS), related to post-zygotic mutations in the GNAS gene, encoding the Gαs subunit of the heterotrimeric G protein." (PMID 34680514, 2021). "These mutations are normally associated with McCune-Albright syndrome (MAS), where mosaic gain-of-function GNAS mutations in patients with MAS lead to the constitutive activation of adenylyl cyclase and to clinical features such as fibrous dysplasia and cafe-au-lait skin pigmentation." (PMID 30208164, 2018). "Hyperthyroidism is also observed in patients with McCune-Albright syndrome (MAS), as a result of the activating somatic mutation of the GNAS gene." (PMID 25908941, 2015). "In McCune-Albright syndrome (MAS), which is caused by mutations in the GNAS gene that encodes the stimulatory subunit α of the G protein, ACAs or, more frequently, BAH are common." (PMID 26042218, 2015). "Somatic activating GNAS mutations cause McCune-Albright syndrome (MAS)." (PMID 23536913, 2013).
McCune-Albright syndrome (continued). "These include pathogenic variants of G protein subunits such as the GNB3 gene in hypertension, activating GNAS variants in McCune-Albright’s syndrome, heterozygous inheritance of inactivating GNAS variants in AHO, and PPH resulting from heterozygous LOF GNAS variants." (PMID 39743506, 2025). "Furthermore, due to a broader coverage of the GNAS gene by the smMIP approach, four novel IM-associated missense mutations of GNAS could be identified (17% of all mutated samples), which previously have only been reported in McCune-Albright syndrome and sporadic endocrine tumors." (PMID 30736805, 2019). "In addition to postzygotic somatic mosaicism of GNAS in McCune-Albright syndrome, rare examples of hereditary PBMAH have been described in the setting of APC-, MEN1-, FH-, PDE8B-, and PDE11A variant-driven pathogenesis." (PMID 29594118, 2018). "McCune-Albright Syndrome (MAS, MIM 174800) is caused by post-zygotic activating mutations in the Gsα subunit of G proteins (encoded by GNAS, MIM 139320), leading to a mosaic distribution of cells bearing constitutively active adenyl cyclase activity." (PMID 29280738, 2017).
Obesity (48 papers, 2011 to 2026). Accumulation of substantial excess body fat. "AHO is another example of syndromic obesity and is associated with variants in GNAS, which encodes the stimulatory G‐protein α subunit of G‐protein–coupled receptors." (PMID 40528426, 2025). "This zebrafish model lays the foundation for efficient functional characterization of GNAS VUSs and paves the way for enhancing our understanding of Gsα deficiency-associated early-onset obesity." (PMID 39684386, 2024). "GNAS mutations can variably impact height as impaired MC4R signalling can lead to obesity with tall stature, whereas impaired GHRH signalling results in GH deficiency and short stature." (PMID 39104441, 2024). "The patient with a GNAS variant had syndromic DOR with major obesity (BMI: 44) as described recently and a thyroid goiter." (PMID 39595984, 2024). "We describe a new missense GNAS variant, c.791A > C, p.(Asp264Thr), in a family with obesity, hyperphagia and mild PTH resistance." (PMID 39104441, 2024). "This study was prompted by identifying several GNAS variants of uncertain significance (VUSs) in pediatric patients presenting with unexplained, severe, early-onset obesity at Sidra Medicine in Qatar." (PMID 39684386, 2024). "Some genetic alterations in specific molecules, especially in children, can lead to obesity, such as those affecting leptin, pro-hormone convertase 1/3, congenital melanocortin-4 receptor deficiency, and GNAS gene mutations." (PMID 38139229, 2023). "Among them, 22 presented with early-onset obesity, and among whom 19 bore heterozygous GNAS mutation, revealing an unexpectedly high prevalence of loss-of-function GNAS mutation among junior obesity patients." (PMID 38017461, 2023). "Among the GNAS rs7121 nucleotide polymorphisms, previous studies indicated that rs7121 is linked to obesity." (PMID 34609028, 2021). "We identified only one rare heterozygous missense variant in GNAS exon XL in a patient with isolated severe obesity." (PMID 32318528, 2020). "We identified one rare heterozygous missense GNAS variant in exon XL (c.897C>A, p.S299R) in a female with severe early-onset obesity." (PMID 32318528, 2020). "We identified 52 variants contributing to obesity in 2% of cases including multiple novel variants in GNAS, which were sometimes found with accelerated growth rather than short stature." (PMID 28663568, 2017). "Maternal inheritance of an inactivating GNAS mutation results in AHO with additional features of obesity and resistance to a variety of hormones, including parathyroid hormone (PTH)." (PMID 23284784, 2012). "Therefore, there is a pressing need for an improved and more robust model organism to facilitate further studies of the pathophysiology of early-onset obesity associated with GNAS changes." (PMID 39684386, 2024). "We report another GNAS variant in 2 patients referred for obesity and their mother." (PMID 39104441, 2024). "For example, it has been reported that patients with single nucleotide polymorphisms (SNPs) in the gene encoding Gαs (GNAS) are associated with increased risk of sudden cardiac death, whereas loss-of-function mutations within GNAS are associated with early-onset obesity." (PMID 34262481, 2021). "GNAS was reported to be associated with obesity and insulin resistance." (PMID 24710015, 2014). "In addition, animal study showed that GNAS knock-out mice with an insertion mutation on maternal allele develops obesity with increased serum leptin levels and lipid accumulation." (PMID 25269528, 2014). "In addition, maternal-specific inheritance of mutations in the GNAS gene can result in severe obesity and resistance to growth-regulating hormones." (PMID 21214909, 2011). "However, GNAS knockdown can cause G protein subunit alpha-s (Gsα) deficiency, which is implicated in several conditions, including certain types of pseudohypoparathyroidism that are often characterized by severe obesity beginning in early childhood." (PMID 41282593, 2025).